MSI1 (musashi RNA binding protein 1)
Diseases named in the same sentence as MSI1 in open-access papers (continued):
Sharing a sentence is not in itself a finding about the gene and the disease.
colon carcinoma (continued). "These evidences displayed the promoting role of MSI1 in colon cancer progression." (PMID 33882945, 2021). "Hence, these evidences indicated that MSI1 knockdown inhibited cell proliferation, migration, and invasion and promoted cell apoptosis and radiosensitivity in colon cancer in vitro." (PMID 33882945, 2021). "The effects of MSI1 on colon cancer progression and radioresistance were revealed in this part." (PMID 33882945, 2021). "Furthermore, MSI1 overexpression also attenuated the impact of circ_0055625 absence on tumor development and radiosensitivity in colon cancer." (PMID 33882945, 2021). "Whether circ_0055625 silencing regulated colon cancer progression and radiosensitivity by downregulating MSI1 expression through sponging miR-338-3p was revealed." (PMID 33882945, 2021). "In colon cancer, MSI1 was reported as tumor marker with prognostic value." (PMID 34062997, 2021). "Further in vitro and in vivo studies showed that (−)-gossypol could repress colon cancer growth through the control of downstream targets of MSI1." (PMID 32340368, 2020). "In addition, AT101 inhibits colon cancer cell growth by targeting MSI1 resulting in reduced Notch/Wnt signaling and cancer growth." (PMID 29296224, 2017). "Moreover, knockdown of MSI1 was found to promote tumor regression and radiation-induced colon cancer cells apoptosis, indicating that MSI1 plays important roles in cancer cell proliferation, inhibition of apoptosis and modulating of tumor progression." (PMID 27285760, 2016). "Previous studies have found that MSI1 knockdown sensitizes colon cancer cells to radiation therapy." (PMID 25940441, 2015). "In the current study, we show that miR-137 can regulate MSI1 in colon cancer cell lines." (PMID 25940441, 2015). "We successfully identified miR-137 as a negative regulator of MSI1 in colon cancer cells." (PMID 25940441, 2015). "An inverse correlation between miR-137 and MSI1 is revealed in a panel of colon cancer cell lines." (PMID 25940441, 2015). "Since MSI1 is overexpressed in the panel of colon cancer cell lines, we hypothesized that miR-137 is down-regulated." (PMID 25940441, 2015). "In addition to reduced MSI1 protein, exogenous expression of miR-137 inhibited cell growth, colony formation, and tumorsphere growth of colon cancer cells." (PMID 25940441, 2015). "Furthermore, this study identified MSI1 as a novel prognostic biomarker and therapeutic target for treating colon cancer." (PMID 25940441, 2015). "Thus, we guessed that circ_0055625 might regulate colon cancer progression and radiosensitivity by miR-338-3p/MSI1 pathway." (PMID 33882945, 2021). "Also, circ_0055625/MSI1-knockdown-directed biomarkers may be employed in further developing targeted drugs of colon cancer." (PMID 33882945, 2021). "In colon cancer cell lines, (−)–gossypol binds to MSI1 with higher affinity than to BCL–2 family members, repressing Notch/Wnt signaling in a MSI1–dependent manner." (PMID 34062997, 2021). "In colon cancer cells, CMLD-1 and CMLD-2 disrupted HuR binding to MSI1 and XIAP mRNAs, and therefore, blocking the Wnt signalling pathway." (PMID 32340368, 2020). "Additional colon cancer cell lines HT29 and HCT-116 β/W were used to validate our findings, both of which displayed reduced MSI1 protein expression in cells transfected with miR-137 mimic." (PMID 25940441, 2015). "In order to determine which miRNAs negatively regulate MSI1 in colon cancer cell lines, miRNA mimics and a negative control (NC) mimic were transfected into high MSI1 expressing cell lines; HCT-116 and DLD-1." (PMID 25940441, 2015). "As a further step aiming at the identification of putative cells with the most stemness features, we carried out co-localization experiments with LGR-5, MSI-1, DCAMKL-1 and nuclear β-catenin, an additional putative marker of stemness, especially in colon cancer." (PMID 23374535, 2013).
colon carcinoma (continued). "The colon cancer derived tumour spheres obtained in this study were evaluated for expression of a panel of stem cell markers, including BMI-1, nestin (NES), and musashi-1 (MSI-1)." (PMID 20332776, 2010). "We used this colon carcinoma cell line rather than HeLa cells because the Wnt signaling pathway is activated and significant levels of TCF7 and MSI1 protein are expressed relative to HeLa cells." (PMID 24551047, 2014).
medulloblastoma (20 papers, 2004 to 2023). A malignant, invasive embryonal neoplasm arising from the cerebellum. "In medulloblastoma, MSI1 was associated with Hedgehog signaling and its depletion sensitized cancer–derived cells toward Hedgehog blockade." (PMID 34062997, 2021). "This subset of cells is strongly associated with the cell cycle and contains multiple Msi1 targets and genes downregulated upon Msi1 knockdown in medulloblastoma cells." (PMID 35011618, 2021). "We established that high expression of Msi1 is often observed in medulloblastoma Group 4 patients and is linked to poor survival." (PMID 35011618, 2021). "In particular, it was shown that the RNA-binding protein Musashi1 (MSI1) is specifically overexpressed in group 4 medulloblastoma, and it correlates with worse prognosis." (PMID 37568705, 2023). "Genomic analyses (RNA-seq and RIP-seq) indicated that cell cycle and division are the main biological categories regulated by Msi1 in Group 4 medulloblastoma." (PMID 35011618, 2021). "In the particular case of medulloblastoma, Msi1 and Msi2 show very distinctive expression patterns in MB subgroups and high Msi2 expression does not show any impact on disease prognosis." (PMID 35011618, 2021). "Genomic analyses (RNA-seq and RIP-seq) showed that cell cycle and cell division are the main biological processes regulated by Msi1 in Group 4 medulloblastoma." (PMID 35011618, 2021). "Cell cycle/division was the common denominator between the RIP-seq and RNA-seq analyses, suggesting that these processes are the main routes used by Msi1 to contribute to Group 4 medulloblastoma." (PMID 35011618, 2021). "We performed a second analysis with HumanBase to expand on biological processes and pathways preferentially regulated by Msi1 in Group 4 medulloblastoma." (PMID 35011618, 2021). "In this study, we evaluated Msi1 in Group 4 medulloblastoma cell lines, showing that its knockdown disrupts cancer-relevant phenotypes." (PMID 35011618, 2021). "MSI1 is also required for tumorigenesis in medulloblastoma and reduction of its expression decreases neurosphere formation, cell proliferation, and tumor growth." (PMID 32448364, 2020). "Msi1 is up-regulated in many cancers, such as medulloblastoma, hepatocellular carcinoma and lung cancer." (PMID 23418578, 2013). "A few reports have been published on the role of MSI1-knockdown (KD) in suppressing tumor-cell proliferation in a medulloblastoma cell line and in adenocarcinoma xenografts in nude mice." (PMID 22428049, 2012). "MSI1-KD in medulloblastoma Daoy cells induces apoptosis and mitotic catastrophe, suggesting a potential mechanism for its role in tumorigenesis." (PMID 22428049, 2012). "We depleted Msi1 in the medulloblastoma cell line Daoy using a vector-based siRNA which targeted a sequence unique for Msi1 located in the 3'UTR of the gene." (PMID 18826648, 2008). "With the high levels of Msi1 reported for medulloblastoma, a connection among Msi1, Notch, Hedgehog and Wnt activities and tumor growth is likely." (PMID 18826648, 2008). "We used the human medulloblastoma cell line Daoy as model system in this study to knock down the expression of Msi1 and determine the effects upon soft agar growth and neurophere formation." (PMID 18826648, 2008). "We defined Musashi1 (Msi1) as one of the main drivers of medulloblastoma development." (PMID 35011618, 2021). "While in medulloblastoma, Msi1 knockdown increased sensitivity to cyclopamine, an SHH inhibitor." (PMID 33804958, 2021). "Since high levels of Msi1 are frequently found in medulloblastoma and since we observed that Msi1 expression was elevated in Daoy neurosphere compared to monolayer cultures, we asked if Msi1 might be involved in regulating proliferation in cancer cells." (PMID 18826648, 2008). "High levels of Msi1 have been found in several malignancies, including medulloblastoma." (PMID 18826648, 2008).
medulloblastoma (continued). "Finally, we determined based on in vitro results that combination therapy (vincristine + luteolin/Msi1 inhibitor) might be a viable alternative to treat Group 4 medulloblastoma patients." (PMID 35011618, 2021). "In these cells, the gene and signaling pathways that are common to several medulloblastoma lineages have been identified, such as NRP1, MSI1, TWIST1, MYCN, and OX2." (PMID 36982406, 2023). "We have identified the stem cell RBP Musashi1 (Msi1) as a key contributor to brain tumor (GBM and medulloblastoma) development and as a marker of clinical outcome and response to therapy." (PMID 33804958, 2021). "The inhibition of Msi1 with luteolin affected the growth of CHLA-01 and CHLA-01R Group 4 medulloblastoma cells and a synergistic effect was observed when luteolin and the mitosis inhibitor, vincristine, were combined." (PMID 35011618, 2021). "We have established Musashi1 (Msi1) as a main player in GBM and medulloblastoma and as a marker of clinical outcome and response to therapy." (PMID 33804958, 2021).
colorectal cancer (18 papers, 2011 to 2024). A primary or metastatic malignant neoplasm that affects the colon or rectum. "The purpose of this study was to identify miRNAs capable of negatively regulating MSI1 in hopes of learning more about the potential cause of MSI1 overexpression in colorectal cancer." (PMID 25940441, 2015). "We propose that a lack of miRNA regulation during proliferation and subsequent differentiation of colon stem cell progeny causes MSI1 overexpression in colorectal cancer." (PMID 25940441, 2015). "MSI1 is a known critical modulator that promotes the development of colorectal cancer stem cells (CSC) and also enhances CRC chemoresistance." (PMID 37686516, 2023). "In colorectal cancer initiation and maintenance, a recent study demonstrated the functional redundancy between MSI1 and MSI2." (PMID 30097032, 2018). "miR-137 negatively regulates the progression of colorectal cancer through directly targeting the oncogenes, such as MSI1, FMNL2 and CDC42." (PMID 29064439, 2017). "Taken together, the data suggests that in normal cells, MSI1 is negatively regulated by miR-137, possibly during differentiation, and this level of regulation has been dismantled in colorectal cancer cells, thus leading to the MSI1 overexpression." (PMID 25940441, 2015). "The objective of this project was to study the post-transcriptional regulation of MSI1 by miRNAs in colorectal cancer." (PMID 25940441, 2015). "Our results demonstrate that miR-137 acts as a tumor-suppressive miRNA in colorectal cancers and negatively regulates oncogenic MSI1." (PMID 25940441, 2015). "We investigated the microRNA (miRNA) regulation of MSI1 and the implications this regulation plays in colorectal cancer." (PMID 25940441, 2015). "Though MSI1 has been identified as a therapeutic target, the molecular mechanisms responsible for overexpression of MSI1 in some colorectal cancers are not well understood." (PMID 25940441, 2015). "We have recently reported that the putative intestinal stem cell marker musashi-1 (Msi-1) regulates Notch-1 in colorectal cancer." (PMID 21929751, 2011). "Furthermore, the RNA-binding protein musashi-1 (MSI1) promotes the formation of SGs in colorectal cancer cell." (PMID 37179344, 2023). "In colorectal cancer, MSI1 promotes the development of CD44 cancer stem cells." (PMID 34604242, 2021). "In colorectal cancer cells, the expression of MSI1 is regulated by Notch 3 signaling." (PMID 32448364, 2020). "Also, it is revealed that MSI1 induces anti-apoptotic stress granule (SG) formation following 5-fluorouracil treatment in colorectal cancers." (PMID 32448364, 2020). "We hypothesized that MSI1-regulating miRNAs are dysregulated in colorectal cancer, producing an over expression of MSI1." (PMID 25940441, 2015). "The molecular mechanism for MSI1 over-expression in colorectal cancer is not well understood." (PMID 25940441, 2015). "One aim of our study was to understand why MSI1 is overexpressed in colorectal cancer." (PMID 25940441, 2015). "Patients with high MSI1 expression was significantly correlated with an increased hazards risk for poor overall survival in patients with bladder cancer (n = 165, P = 0.0150), AML (n = 34, P = 0.0002), colorectal cancer (n = 55, P = 0.0151) and ovarian cancer (n = 133, P = 0.0019)." (PMID 25940441, 2015). "In CRC, Musashi-1 (MSI1) plays a role in enhancing chemoresistance and enhancing the development of CD44+ colorectal cancer stem cells (CSCs)." (PMID 39456596, 2024). "We utilized a panel of previously characterized human colorectal carcinoma cell lines to compare LGR5 expression to the expression of another putative intestinal stem cell marker, Musashi-1 (Msi-1)." (PMID 21829496, 2011). "It had been confirmed that Msi1 could bind to the 3' UTR of the PTEN mRNA, decreasing PTEN protein levels in human colorectal cancer (CRC) cells." (PMID 33758618, 2021). "Therefore, inhibition of both MSI1 and MSI2 are required to fully abrogate tumor growth in colorectal cancer cell lines." (PMID 29064439, 2017).
endometrial carcinoma (18 papers, 2010 to 2024). A malignant tumor arising from the epithelium that lines the cavity of the uterine body. "Msi-1 has also been demonstrated to be overexpressed in endometrial stem cells and to be associated with stem cell pathways both in endometrial cancer and endometriosis." (PMID 35619161, 2022). "Msi1 appears to be strongly associated with tumor progression in human somatic tumors, including endometrial cancer, gastric cancer and esophageal adenocarcinoma." (PMID 25362645, 2014). "To note, notch-1, and its modulator MSI1 are expressed in the human endometrium, and have been linked to a putative dysregulation of endometrial stem cell function in endometriosis and endometrial carcinoma." (PMID 20585575, 2010). "MSI-1, a stem cell marker known to be dysregulated in endometriosis and endometrial cancer, was expressed in around two-thirds of the tissue samples in the AM group, in contrast to only about one-third in the non-AM group." (PMID 39595532, 2024). "Overall, silencing of MSI-1 presented as a potential therapeutic option regarding tumor growth and radiation therapy in MSI-1 expressing endometrial cancers." (PMID 37620963, 2023). "Consistent with previous data on Ishikawa endometrial carcinoma cells subjected to MSI-1 siRNA knockdown, the cell cycle regulator p21WAF1/CIP1 was upregulated in MSI-1 and -2 depleted 12-Z cells compared to controls." (PMID 35269992, 2022). "In the present study, we show decreased cell proliferation and radioresistance after siRNA-mediated Msi-1 knockdown in two endometrial carcinoma cell lines." (PMID 35619161, 2022). "MSI-1 has been demonstrated to modulate development of endometrial cancer and to be significantly upregulated in endometriotic tissue." (PMID 35269992, 2022). "Previous studies in small patient cohorts pointed to a high Msi-1 expression in endometrial cancer patients." (PMID 35619161, 2022). "Taken together, our findings indicate that Msi-1 targeting is a therapeutically interesting option to decrease endometrial cancer cell proliferation and radioresistance." (PMID 35619161, 2022). "It was reported that Msi1 modulated cell cycle progression and apoptosis via Notch-1 and p21 in endometrial carcinoma, and Msi1 modulated mammary progenitor cell expansion through the activation of the Wnt and Notch pathways." (PMID 25362645, 2014). "The Msi1 protein can also be found in tissues from patients with endometriosis and endometrial carcinoma, photoreceptor cells, retinal stem cells, and the hair follicle stem cell nich." (PMID 22026428, 2011). "MSI-1 was overexpressed in CSCs in endometrial cancer tissue." (PMID 37620963, 2023). "MSI1–directed cell cycle control was also reported in endometrial cancer." (PMID 34062997, 2021). "A previous study showed direct regulation of p21 by MSI-1 and regulatory effects via NOTCH in endometrial carcinoma." (PMID 34768932, 2021). "Given that TCGA database analyses for this study identified Notch-1 as a negative prognostic marker in endometrial carcinoma (p = 0.004), we tried to characterize the relationship between Msi-1 and Notch-1." (PMID 35619161, 2022).